HIF1A (hypoxia inducible factor 1 subunit alpha)
Diseases named in the same sentence as HIF1A in open-access papers (continued):
Sharing a sentence is not in itself a finding about the gene and the disease.
breast cancer (continued). "Moreover, DDX3X expression in breast cancer was found to be increased by hypoxia-inducible factor 1-alpha (HIF-1α), a transcription factor that induces the transcriptional activation of DDX3X via binding to the HIF-responsive element located in the DDX3X promoter." (PMID 35954483, 2022). "Similarly, UCA1 overexpression blocks apoptosis of breast cancer cells by HIF1A inhibitor." (PMID 36230902, 2022). "In contrast, in breast cancer cells, HIPK2 is degraded during periods of low oxygen via association with the E3 ubiquitin ligase SIAH2; this degradation of HIPK2 is necessary as the protein normally represses the expression of HIF-1α by binding at its promoter." (PMID 35285794, 2022). "Hypoxia-induced alternative splicing also impacts the regulation of glycolysis through HIF-1α-mediated splicing of glycolytic enzymes Hk1 and Pfkfb3 in myocardial hypoxia, as well as differential regulation of lactate dehydrogenase (LDHA) variants through intron retention in breast cancer cells." (PMID 35330188, 2022). "However, little is known about the predictive value of HIF-1α response in breast cancer." (PMID 36358811, 2022). "Similarly, circ_0003575, circ_0003204, circ_002136, and circ-001971/miR-29c-3p plays an important role in angiogenesis,circ_001621/miR-578 regulates VEGF/HIF-1α axis controlling breast cancer angiogenesis, circ_0007059/miR-378 regulates EMT transition in lung cancer cells." (PMID 33763348, 2021). "Moreover, studies on ovarian and breast cancer revealed that OPN could promote the expression of HIF-1α in a PI3k/AKT pathway-dependent manner and then regulate TWIST1 gene to monitor EMT." (PMID 34070192, 2021). "In addition, we suggested evidence that sensitivity of paclitaxel resistant breast cancer cells to this combination treatment correlates with EMT process by blocking HIF-1α, vimentin, Snali, and Slug and by activating E-cadherin in paclitaxel resistant breast cancer cells." (PMID 34942984, 2021). "Likewise, the chemokine receptor CXCR4 has multiple upstream mediators, with upregulation in renal cell carcinoma described in response to hypoxia inducible factor (HIF1a) and galectin 1, and in breast cancer with angiotensin II type I receptor (AGTR-1) and NF kappa B." (PMID 33927349, 2021). "However, HIF-1α promotes CLDN6 transcription in hypoxic cultured breast cancer cells." (PMID 34948213, 2021). "Thus, HIF-1α has been well-documented for its important role in supporting metastasis and drug resistance in breast cancer, and inhibition of this protein has been regarded as an essential strategy in breast cancer treatment." (PMID 34208576, 2021). "Moreover, both phytochemicals negatively regulate HIF-1α expression in breast cancer." (PMID 34575983, 2021). "In addition, RhoA was reported to be a direct target of HIF1A in breast cancer cells." (PMID 33875796, 2021). "Hypoxia and activation of HIF1α as well as HIF2α is known to contribute to tumor progression and metastasis in various organs including breast cancer, but besides the studies by Devignes and colleagues little is known about the impact of hypoxia in breast cancer bone metastasis." (PMID 32232008, 2020). "In an experiment on breast cancer cells in a hypoxic environment, researchers found that circZNF292, circDENND4C, and circSRSF4 were upregulated after hypoxia treatment, while among these, only circDENND4C was demonstrated to be activated by the induction of HIF-1α." (PMID 32014012, 2020). "Therefore, the activation of ERK/HIF-1α/EMT signaling by XCL1 may specifically mediate the migration of breast cancer cells, including MDA-MB-231 and SK-BR-3 cells." (PMID 33374849, 2020). "Additionally, the discovery of small molecular compounds interfering with the cooperation of HIF‐1α/STAT3 may gain more insights to the clinical treatment for breast cancer." (PMID 32065498, 2020).
breast cancer (continued). "Leptin signaling may lead to STAT3 activation of HIF-1α in breast cancer and therefore may also drive CPT1 expression resulting in nuclear regulation of energy generation; a critical activity for cellular survival particularly in unfavourable hypoxic environments." (PMID 32331320, 2020). "However, the interaction between HIF‐1α and Kindlin‐2 and the relevant mechanism of the breast cancer stiffness remains unclear." (PMID 32436609, 2020). "Therefore, based on SWE, Emax could be a physical biomarker of invasive breast cancer for early, noninvasive diagnosis, and HIF‐1α and Kindlin‐2 could be pathological markers for early diagnosis and targeted therapy." (PMID 32436609, 2020). "Our data support the hypothesis that breast cancer patients with primary CLDN6 loss are more likely to have tumour metastasis due to lack of feedback mechanism to inhibit HIF-1α stability." (PMID 32093760, 2020). "In both mouse breast cancer xenograft and zebrafish xenotransplantation models, SA inhibited breast cancer growth and inhibited late-phase autophagy in vivo, which was accompanied by suppression of Hif-1α/Cav-1 signaling and the epithelial-mesenchymal transition." (PMID 33381039, 2020). "We aim to evaluate whether the quantitative gene and protein expression of hypoxic response tumor markers — carbonic anhydrase IX (CAIX) and hypoxia- inducible factor 1 alpha (HIF1A) — may have a role in predicting survival in advanced breast cancer of Indonesian population." (PMID 32212787, 2020). "However, whether the regulation of breast cancer progression by LNT has the involvement of HIF-1α remains elusive." (PMID 33245358, 2020). "Therefore, in our next study, we plan to investigate whether Cav-1 transcription can be directly regulated by Hif-1α in human breast cancer, and whether SA can interrupt this interaction." (PMID 33381039, 2020). "Furthermore, HIF-1α expression has been reported to be correlated with MDR in breast cancers." (PMID 31505803, 2019). "HIF-1α may be a target for the treatment of breast cancer–related coagulation and thrombosis." (PMID 31711497, 2019). "Indeed, BRAF has been incriminated in the MAPK pathway overstimulation, resulting in the downstream stabilization of the hypoxic inducible transcription factor-1alpha (HIF-1α) in BRAFV600E melanoma, a transcription factor also overexpressed in the BRAF-mutated MDA-MB-231 breast cancer cell lines." (PMID 31744229, 2019). "Thus, it is worth exploring whether and how the Rac1/HIF-1α pathway is involved in SOX2-mediated breast cancer cell motility." (PMID 31462898, 2019). "Thus, supplementation of vitamin C could help decrease HIF-1α levels in breast cancer, which may be beneficial for blocking metastasis." (PMID 31817810, 2019). "Based on our previous observation of the role of miR-181c-5p (miR-181c) in MT-CO1 suppression and consequent reduction in MMP and ATP production in NRF2-knockdown colon cancer cells, we speculated that miR-181c is involved in HIF-1α dysregulation in NRF2-silenced breast cancer cells." (PMID 31078780, 2019). "To further explore whether CpG and non CpG methylation within the HIF-1α gene promoter may determine the HIF-1α expression level in breast cancer cell lines, we detected and analyzed the CpG and non CpG methylation status of the HIF-1α promoter in MCF-7 after 5-Aza treatment." (PMID 30940798, 2019). "Furthermore, elevated HIF-1α levels are also associated with HER2 overexpression, as well as increased VEGF, COX-2, and Ki67 levels, suggesting that HIF-1α is strongly linked to more aggressive forms of breast cancer." (PMID 29628507, 2018). "The translational implications of the interdependence between estrogenic and hypoxic signaling mediated by ER and/or GPER together with HIF-1α could deeply impact the development of novel combination strategies aimed at inhibiting breast cancer progression and overcoming anti-cancer drug resistance." (PMID 29996493, 2018).
breast cancer (continued). "Our studies in the 4T1 murine model of aggressive/metastatic breast cancer provide direct evidence that tumor cell metabolism (high LDH-A expression) is associated with a “poor prognosis” phenotype, and is mediated through more robust HIF-1α and downstream target responses to hypoxia." (PMID 30248111, 2018). "Also, it was shown that TAZ and HIF1α interaction progresses breast cancer metastasis." (PMID 30619734, 2018). "Likewise, cytokines as TGF-β and IL-1β may be released by breast cancer cells in a HIF-1α dependent manner and promote the conversion of normal fibroblasts to CAFs, hence encouraging tumor growth, metastatic spread, and neoangiogenesis." (PMID 29996493, 2018). "Additionally, HIF-1α displays two expression patterns: a canonical hypoxia-related perinecrotic pattern and a diffuse expression pattern, both related to a poor clinical outcome in breast cancer." (PMID 29228687, 2017). "Moreover, blockade of HIF-1α enhanced the efficacy of a DC vaccine in a murine breast cancer model, an effect that could be due to reduction of PD-L1 by blocking HIF-1α." (PMID 29081778, 2017). "As PHD3 has been shown to promote degradation of HIF-1α and HIF-1α has been shown to play key roles in many crucial aspects of breast cancer biology, including invasion and metastasis, we hypothesized that HIF-1α could be a mediator of the invasive effects of ERβ2 in this system." (PMID 29100336, 2017). "Because hypoxia-induced ALKBH5 expression is HIF-dependent in breast cancer cell lines and human breast cancers are hypoxic, with a median pO2 of 10 mm Hg (∼1.5% O2), we hypothesized that ALKBH5 and HIF-1α expression should be correlated in breast cancer tissue." (PMID 27590511, 2016). "Thus, ALKBH5 and HIF-1α expression were concordant in all 9 breast-cancer biopsies analyzed." (PMID 27590511, 2016). "Furthermore, ERα has been reported to directly induce HIF-1α transcription, which might modulate the anti-estrogen response in breast cancer treatment." (PMID 27105516, 2016). "In addition, zoledronic acid may overcome endocrine resistance in ER-positive human breast cancer by targeting HIF-1α transcription through inhibition of the RAS/MAPK/ERK1/2 pathway." (PMID 25929338, 2015). "Moreover, the half-life assays showed that HBXIP overexpression could obviously suppress the degradation of HIF1α, suggesting that HBXIP contributes to the stability of HIF1α in breast cancer cells." (PMID 26309161, 2015). "Based on these findings, the prospects of using anti-HIF-1α therapy is not likely to favor TNBC over other tumor groups, however, targeting HIF-1α may still prove beneficial given its definite expression in a significant portion of all studied breast cancer subtypes." (PMID 26046764, 2015). "Since HIF-1α expression is associated with poor clinical outcome in breast cancer patients and we show that hypoxia via HIF-1α reduces DUSP2 expression, we interrogated whether DUSP2 expression may also be associate with poor clinical outcome in breast cancer patients." (PMID 25596742, 2015). "To confirm that inhibition of HIF-1α resulted in upregulation of NFκB in hypoxic breast cancer cells in the presence of IL-1β, we decided to perform similar experiments by using Topotecan, a topoisomerase inhibitor which has been described also as a pharmacological inhibitor of HIF-1α." (PMID 26696754, 2015). "Importantly, HIF-1α is a key factor responsible for the transcriptional regulation of genes that facilitate the stemness properties of cancer cells and enhance their metastatic potential in leukemia and in prostate and breast carcinomas." (PMID 26528854, 2015). "We evaluated whether proline-hydroxylated HIF-1α was prognostic in primary breast cancer." (PMID 24563687, 2014).
breast cancer (continued). "Our finding that hydroxylated HIF-1α in primary breast cancer is associated with significantly poorer survival (unlike total HIF-1α) suggests that a more moderate level of hypoxia that allows for continued HIF-1α hydroxylation may favour malignant progression." (PMID 24563687, 2014). "Results in these studies demonstrate that exposure to 150uM CoCl2 cause a hypoxic response in +SA mammary tumor cells grown in culture, as evidenced by the large increased expression of the hypoxia-inducible factor, HIF-1α, without causing significant adverse effects on +SA cell viability or growth." (PMID 25140303, 2014). "Additionally, after treatment with radiation (10 Gy), sorafenib (5 and 10 μg/ml), radiation + sorafenib (10 Gy + 5 μg/ml and 10 Gy + 10 μg/ml) or DMSO for 72 h, immunoblotting of breast cancer cells under hypoxic and normoxic conditions showed different HIF-1α expression patterns." (PMID 23314174, 2013). "Moreover, Bos and collaborators have shown the association between HIF-1α and angiogenesis in invasive breast cancer, and the study of Hansen S. has demonstrated that MVD can independently predict poor prognosis in operable breast cancers." (PMID 23326384, 2013). "In support of this, a direct relationship between the co-expression of HIF-1α and the CD44+/CD24−/low phenotype has been observed by immunohistochemical analyses of 253 samples of breast ductal carcinoma from patients, and associated with a worse prognosis of breast cancer patients." (PMID 23301832, 2013). "Indeed, leptin levels were increased under hypoxia in trophoblasts and breast cancer via HIF-1α." (PMID 24202338, 2013). "The effect of YC-1 could therefore be 2-fold; inhibition of HIF-1α and downregulation of PR, making it a uniquely suitable small molecule drug for combating those forms of breast cancer which are largely dependent on the actions of progestins to stimulate the production of VEGF." (PMID 23123638, 2013). "Moreover, we confirmed that antagomir-21 could suppress miR-21 expression in breast tumor tissues, which is involved in inhibiting angiogenesis by targeting HIF-1α/VEGF/VEGFR2 signaling pathway in breast cancer." (PMID 23951172, 2013). "Thus, it is worthwhile to explore whether PI3K and ERK signaling pathways are involved in hypoxia-induced Rac1 activation and HIF-1α induction in breast cancer cells." (PMID 21980400, 2011). "Cellular iron deficiency increased HIF-1α, VEGF, and angiogenesis, suggesting that systemic iron deficiency might play an important part in the tumor angiogenesis and recurrence in this young age group of breast cancer patients." (PMID 20723262, 2010). "Our study has demonstrated an important role for cellular iron deficiency in HIF-1α stabilization, VEGF formation, and angiogenesis, suggesting that systemic iron deficiency and anemia in young breast cancer patients may make them more susceptible to tumor recurrence through the same mechanism." (PMID 20723262, 2010). "EGCG, the predominant catechin in green tea, inhibits HIF-1α stabilization and VEGF expression, which have a critical role in breast cancer tumor angiogenesis." (PMID 41614951, 2026). "In vivo, animal models inoculated with E0771 breast cancer cell line, a luminal-B like model, further confirms EGFG’s inhibition of angiogenesis and breast cancer progression due to lesser levels of VEGF and HIF-1α, along with NFκB." (PMID 41614951, 2026). "Collectively, these findings underscore the potential of HIF-1α, CD44, and STC2 as both biomarkers and therapeutic targets in the management of breast cancer bone metastasis." (PMID 41596432, 2026). "In vitro, its EF24 analogue has been shown to decrease HIF-1α protein and disrupt hypoxia signaling in MDA-MB-231 breast cancer cells." (PMID 41614951, 2026). "Mechanistically, YTHDF3 enhances the expression of HIF1α and LDHA and glycolysis by inducing the phosphorylation of mTOR, and finally promotes the occurrence and development of breast cancer." (PMID 42036761, 2026).
breast cancer (continued). "Although both sulforaphane and curcumin show promise in inhibiting HIF-1α and VEGF, further research must be carried out to support similar findings in breast cancer." (PMID 41614951, 2026). "miR-138-5p inhibits HIF-1α/VEGFA signaling and vascular mimicry in hepatocellular carcinoma and suppresses EMT/migration in breast cancer, indicating its anti-angiogenic role in multiple contexts." (PMID 41516402, 2026). "Breast cancer cell-derived extracellular vehicles (EVs) deliver miRNA to target the VHL gene, leading to the upregulation of hypoxia-inducing factor 1A (HIF1A) in WAT." (PMID 41498391, 2026). "When HIF-1α is activated, VEGF, which provides nutrition and oxygen to rapidly proliferating breast cancer cells, is increased." (PMID 41614928, 2026). "In vitro, EGCG decreased the expression of HIF-1α and VEGF in MCF-7 breast cancer cells, inhibiting angiogenesis and cell growth." (PMID 41614951, 2026). "This transition is regulated by HIF-1α-mediated factors, including SNAIL, SLUG, TWIST 1, and ZEB, which collectively promote VM formation in breast cancer." (PMID 41400702, 2025). "In breast cancer, HEXIM1 can weaken the interaction between HDAC1 and HIF‐1α, leading to the acetylation of HIF‐1α and reducing the expression of its target genes, thereby inhibiting cell invasion." (PMID 39778006, 2025). "Not only are HIF1A and WWOX differentially expressed between malignant and benign breast cancer tissue, but this is also true for the expression of key glycolysis genes." (PMID 41007296, 2025). "The distinct roles of HIF-1α and HIF-2α in regulating different aspects of tumor biology make them both essential players in breast cancer progression." (PMID 40901111, 2025). "In the same study, IFN-α also increased HIF-1α expression in MCF-7 and MDA-MB-231 breast cancer cells, suggesting that components of this signaling network are present and responsive in breast cancer." (PMID 41400702, 2025). "In breast cancer, hypoxia-inducible factor 1α (HIF1α) and HIF-2α stimulate the expression of ALKBH5 which can demethylate NANOG mRNA and increase its stability, inducing the breast cancer stem cell (BCSC) phenotype." (PMID 40483535, 2025). "In breast cancer, TIM and CDCA5 activate mTORC1/PI3K/AKT signaling, suppressing apoptosis while enhancing glycolysis through GLUT1/4 upregulation and HIF1α/c-Myc-mediated glycolytic enzyme synthesis." (PMID 41009376, 2025). "This study aimed to investigate the impact of E2 on TRPV1 expression, hypoxia-inducible factor-1α (HIF-1α), and calcium signaling in MCF-7 breast cancer cells (ERα-positive) and TRPV1-transfected CHO cells (ERα-negative)." (PMID 41303593, 2025). "DHA was shown to reduce the expression of HIF-1α and its target genes, such as the glucose transporter 1 and lactate dehydrogenase, in BT-474 and MDA-MB-231 breast cancer cells." (PMID 39863855, 2025). "In contrast, in luminal A breast cancer subtype, our results reveal a more complex and, at times, paradoxical relationship with the WWOX/HIF1A ratio." (PMID 41007296, 2025). "In HER2-overexpressing SKBR3 breast cancer cells with trastuzumab resistance, STAT3/HIF-1α axis-mediated Hes1 induction downregulates PTEN, positioning Hes1 as a pivotal node linking STAT3 signaling to PTEN suppression." (PMID 40755759, 2025). "These molecular alterations are evident in breast cancer subtypes (basal, HER2-positive, luminal A and B), HCC, GBM, and LGG, underscoring the universal relevance of the WWOX/HIF1A axis in tumour biology." (PMID 41007296, 2025). "In a breast cancer lung metastasis model, mice injected with CTC clusters exhibited significantly larger HIF-1α-positive areas in lung tissues compared to those receiving single CTCs." (PMID 41381723, 2025).